RBMS3 (RNA binding motif single stranded interacting protein 3)
Description:
Binds poly(A) and poly(U) oligoribonucleotides.
Tractability: PROTAC: ubiquitination databases record sites on it.
Gene: Protein-coding gene on chromosome 3 (28,574,791 to 30,010,391, forward strand). Ensembl gene ENSG00000144642.
Subcellular location: Cytoplasm
Subcellular location (Human Protein Atlas): Vesicles
Gene Ontology:
Molecular function: mRNA 3'-UTR AU-rich region binding; poly(A) binding; poly(U) RNA binding; mRNA 3'-UTR binding; nucleic acid binding; RNA binding
Biological process: defense response to tumor cell; negative regulation of canonical Wnt signaling pathway; negative regulation of gene expression; positive regulation of gene expression
Cellular component: cytoplasm; cytosol; nucleus; ribonucleoprotein complex
Genetic constraint (gnomAD): Loss-of-function variants: 22 observed, 53.31 expected, observed/expected ratio (o/e) 0.41, 90% interval 0.29 to 0.59. The upper end of that interval is the gene's LOEUF score, 0.59, which puts it in group 2 of 6, group 1 being the genes least tolerant of losing a copy. Missense variants: 469 observed, 516.81 expected, observed/expected ratio (o/e) 0.91, 90% interval 0.84 to 0.98. Synonymous variants: 177 observed, 175.25 expected, observed/expected ratio (o/e) 1.01, 90% interval 0.89 to 1.14.
Homologues: Orthologues: chimpanzee RBMS3 (100% identical), macaque RBMS3 (99% identical), rabbit RBMS3 (99% identical), dog RBMS3 (95% identical), pig RBMS3 (94% identical), mouse Rbms3 (90% identical), rat Rbms3 (90% identical), guinea pig RBMS3 (89% identical), tropical clawed frog rbms3 (88% identical), zebrafish rbms3 (79% identical). Paralogues in human: RBMS1 (68% identical), RBMS2 (62% identical), PABPC1 (27% identical), PABPC3 (25% identical), PABPC1L (25% identical), ELAVL2 (24% identical), ELAVL4 (24% identical), PABPC4 (24% identical), PUF60 (22% identical), ELAVL3 (22% identical), SYNCRIP (20% identical), ELAVL1 (20% identical), and 12 more.
Diseases named in the same sentence as RBMS3 in open-access papers:
RBMS3 is named in the same sentence as 48 diseases in open-access papers, as found by Europe PMC text mining. Sharing a sentence is not in itself a finding about the gene and the disease. The quoted sentences say what the papers report.
breast carcinoma (19 papers, 2018 to 2025). "RNA Binding Motif Single Stranded Interacting Protein 3 (RBMS3) is a known tumor suppressor in breast cancer and is significantly associated with the epithelial to mesenchymal (EMT) transition, especially in TNBC." (PMID 37621676, 2023). "RBMS3 can be an indicator of longer overall survival for potential use in breast cancer diagnostic process." (PMID 36769184, 2023). "Although further studies on the exact molecular mechanisms underlying the role of RBMS3 in breast cancer are required, RBMS3 may be potentially used in the development of novel therapeutic and diagnostic approaches in breast cancer." (PMID 36769184, 2023). "In addition, ANGPT1, PRG4, and RBMS3 were found to be mutated within a portion of the TCGA breast cancer samples." (PMID 37621676, 2023). "RBMS3 also significantly inhibited the expression of β-catenin, cyclin D1 and c-Myc proteins in breast cancer cells." (PMID 38783078, 2024). "Overexpression of RBMS3 significantly inhibited the proliferation, migration and invasion of breast cancer cells." (PMID 38783078, 2024). "By analysing DERBPs and differential AS in breast cancer tissues in TCGA, it was found that the expression levels of RBPs such as RBMS3 and the pSAR values of AS occurring on TNC and COL6A3 were significantly correlated with the prognosis of patients." (PMID 38783078, 2024). "We found that the expression of RBMS3 was significantly reduced in both breast cancer tissue and metastatic breast tissue compared to normal tissue." (PMID 38783078, 2024). "Previous studies have reported on the tumor‐suppressive functions of RBMS3 in various cancers, such as breast cancer, esophageal squamous cell carcinoma, and nasopharyngeal cancer." (PMID 38618967, 2024). "The transcriptomic analysis of the RBMS3 gene’s expression in the stromal cells of breast cancer provides evidence of its being gradually downregulated through all three grades of breast cancer." (PMID 36769184, 2023). "Although RBMS3 seems to play a major role in carcinogenesis, there remains a need for extensive research because of its complex influence on breast cancer." (PMID 36769184, 2023). "In this study, we have discussed the role of RBMS3 in the progression of breast cancer with particular emphasis on receptor expression and the molecular type." (PMID 36769184, 2023). "RBMS3 is reported to be deregulated in many different types of neoplastic processes, for example, gastric cancer, esophageal squamous cell carcinoma, breast cancer, or gall bladder carcinoma." (PMID 36769184, 2023). "Taking into consideration all the results presented in this study, we provide evidence of a potential novel explanation of RBMS3′s role in breast cancer." (PMID 36769184, 2023). "RBMS3, through inactivation of the Wnt/β-catenin signaling pathway, also inhibits proliferation and tumorigenesis of breast cancer cells." (PMID 37621676, 2023). "In breast cancer, RBMS3 plays a pivotal role in maintaining the mesenchymal phenotype, invasiveness, and migratory ability." (PMID 37781074, 2023). "In this current study, we provide evidence of RBMS3′s potential use as a positive prognostic marker of overall survival in breast cancer." (PMID 36769184, 2023). "RBMS3 is considered a novel malignancies inhibitor gene, including in breast cancer, esophageal squamous cell carcinoma, and nasopharyngeal carcinoma, thus attracting widespread attention." (PMID 36897170, 2023). "It has been reported that RBMS3 participates in the carcinogenesis process of breast cancer, since it is often described as a suppressor protein." (PMID 36769184, 2023). "Low expression of RBMS3 in breast cancer tissue is significantly negatively correlated with poor prognosis." (PMID 37968257, 2023). "We distinguished a positive correlation with overall survival, supporting the idea of a potential tumor-suppressing role for the expression of RBMS3 in breast cancer stroma." (PMID 36769184, 2023).
breast carcinoma (continued). "Recent studies have demonstrated that RBMS3 is aberrantly expressed in various cancers, including breast cancer 36, ovarian cancer 37, and prostate cancer." (PMID 37781074, 2023). "Previous studies have suggested that the long non-coding RNA MEG3 upregulates RBMS3 expression, thereby inhibiting breast cancer proliferation and apoptosis." (PMID 37781074, 2023). "Another mechanism of influence of RBMS3 in breast cancer is its presence in the miR-141-3p/RBMS3 axis that inhibits proliferation and promotes apoptosis in breast cancer cells." (PMID 36769184, 2023). "A further aim of this study is to discuss RBMS3 as a novel potential therapeutic target and biomarker of overall survival in breast cancer." (PMID 36769184, 2023). "Another study conducted on breast cancer provided interesting data stating that the expression of RBMS3 is a required factor for EMT induction in immortalized mammary epithelial cell lines." (PMID 36142783, 2022). "RBMS3 greatly inhibited the protein expression of β-catenin, cyclin D1, and c-Myc in breast cancer cells." (PMID 34804951, 2021). "Another study found that RBMS3 inhibited breast cancer cell proliferation, migration, and invasion through the Wnt/β-catenin signalling pathway." (PMID 33685397, 2021). "RBMS3 was downregulated in breast cancer and ectopic expression of RBMS3 contributed to inhibition of cell migration, invasion in vitro and lung metastasis in vivo." (PMID 30819235, 2019). "Transwell and in vivo metastasis assay were conducted to investigate the effects of RBMS3 on migration, invasion and metastasis of breast cancer cells." (PMID 30819235, 2019). "In the present study, we demonstrated that RBMS3 played a critical role in the metastasis of breast cancer." (PMID 30819235, 2019). "In summary, we demonstrated that the RBMS3 was a novel target for metastasis inhibition in breast cancer." (PMID 30819235, 2019). "We provided a novel mechanism that the basic helix-loop-helix transcription factor Twsit1, the key regulator in cancer metastasis, was regulated by RBMS3 in breast cancer cells in vitro and in vivo." (PMID 30819235, 2019). "Our study implied that RBMS3-mediated decrease in Twist1 expression played a crucial role in the breast cancer metastasis process." (PMID 30819235, 2019). "Quantitative real-time PCR and western blots were carried out to determine the expression of RBMS3 in breast cancer cells and tissues." (PMID 30819235, 2019). "Breast cancer cell lines and tissue samples were used to detect the expression level of RBMS3, followed by western blot and qRT-PCR analysis." (PMID 30819235, 2019). "Kaplan-Meier analysis revealed that upregulation of RBMS3 was correlated with better prognosis (HR = 0.61) in breast cancer patients." (PMID 30819235, 2019). "RBMS3 was also identified to be a potential treatment target in breast cancer which inhibited the proliferation and invasion of breast cancer." (PMID 30514345, 2018). "RBMXL2 had a very low expression in both breast tissue and cancer in TCGA database and RBMS3 was reported to be a tumor suppressor in breast cancer." (PMID 30514345, 2018). "Among these concordantly methylated genes, several have known tumor-suppressive activities in PCa, including ERBB4, MCPH1, RBMS3, and AKAP12, High DNA methylation levels of ERBB4 have been associated with poor prognosis and aggressive disease in breast cancer patients." (PMID 40723280, 2025). "Previous studies have revealed the regulatory role of RBMS3 in deactivating the Wnt/β‐catenin signaling pathway and repressing the expressions of diverse genes, including β‐catenin, cyclin D1, and C‐myc, within breast cancer cells." (PMID 38618967, 2024). "We constructed a risk model based on the expression levels of these RBPs and found that ADAT2, C2orf15, SRP72, PAICS, RBMS3, APOBEC3G, NOA1, and ACO1 could be used for risk assessment in terms of breast cancer prognosis." (PMID 38783078, 2024).
breast carcinoma (continued). "Moreover, overexpressed lncMEG3 inhibited the growth of breast cancer cells, and promoted apoptosis via regulating the miR-141-3p/RBMS3 axis." (PMID 38271137, 2024). "The currently postulated mechanisms explaining the role of RBMS3 in the progression of breast cancer include involvement in the epithelial–mesenchymal transition (EMT) by inhibiting the Wnt/β-catenin signaling pathway and other EMT-related transcription factors, such as TWIST1 or PRRX1." (PMID 36769184, 2023). "Additionally, using the Kaplan–Meier estimator we performed an analysis of the RBMS3 mRNA expression of 2976 cases of breast cancer." (PMID 36769184, 2023). "Together, these data suggest that RBMS3′s deregulation in the stroma of the tumor may influence the role of stromal cells in breast cancer through currently unknown mechanisms." (PMID 36769184, 2023). "The aim of this study is to discuss the role of RBMS3 in breast cancer." (PMID 36769184, 2023). "There is also evidence that the expression of RBMS3 in the stroma cells of breast cancer could have an impact on the progression of BC." (PMID 36769184, 2023). "RBMS3 inhibits breast cancer metastasis by regulating Twist1 expression." (PMID 37968257, 2023). "Cytoplasmatic RBMS3 IHC expression was observed in breast cancer cells and stromal cells." (PMID 36769184, 2023). "A higher expression of RBMS3 in the stroma of breast cancer may indicate the potentially important role of the TME in the progression of IDC." (PMID 36769184, 2023). "Further investigation in the stroma of breast cancer showed significant increases in RBMS3 expression in the specimens with positive expression of the progesterone receptor and samples with positive expression of the estrogen receptor (respectively, Mann–Whitney test p < 0.01 and p < 0.001)." (PMID 36769184, 2023). "Using immunohistochemical staining performed on paraffin-embedded blocks of breast cancer samples and molecular analysis performed with breast cancer cells from cell-line cultures, we showed the correlation between RBMS3 levels and particular intrinsic subtypes of BC." (PMID 36769184, 2023). "Specifically, a negative correlation with TNBC may indicate the tumor-suppressor role of RBMS3 in breast cancer stroma." (PMID 36769184, 2023). "The analysis of RBMS3 mRNA expression in samples from the GEO and EGA data repositories also supports the suggestion that RBMS3 may be a useful tool for breast cancer diagnosis." (PMID 36769184, 2023). "For further investigation of the difference in RBMS3 expression in the different molecular types of breast cancer, we performed an RT-qPCR analysis of RBMS3 expression at the mRNA level in the chosen cell lines representing the various molecular types of breast cancer." (PMID 36769184, 2023). "Currently available reports have tried to explain RBMS3′s anticancer activity in all types of breast cancer through the inhibition of the Wnt/β-catenin pathway and the inhibition of the epithelial–mesenchymal transition process (EMT), mainly by impacting on TWIST, PRRX1, or MMP2." (PMID 36769184, 2023). "Moreover, a recent study showed that the RBMS3 gene expression in the tumor-associated stromal cells of breast tumor was gradually downregulated among grade I, II, and III of breast cancer." (PMID 36142783, 2022). "MEG3 could up-regulate OTU deubiquitinase 4 (OTUD4) and RNA binding motif single-stranded interacting protein 3 (RBMS3) by sponging miR-494 and miR-141-3p, respectively, thereby suppressing breast cancer cells proliferation." (PMID 36551518, 2022). "The role of RBMS3 has been most extensively explored in breast cancer among all types of cancer." (PMID 36142783, 2022). "Furthermore, RBMS3 was found to inhibit the proliferation and tumorigenesis of breast cancer cells, at least in part, through inactivation of the Wnt/β-catenin signaling pathway." (PMID 30819235, 2019). "However, there were few studies on the role of RBMS3 in the metastasis of breast cancer and related mechanism." (PMID 30819235, 2019).
breast carcinoma (continued). "In the present study, we revealed that RBMS3 could inhibit breast cancer metastasis in vitro and in vivo." (PMID 30819235, 2019). "Then, transwell assays was carried out to examine whether RBMS3 had the ability to suppress breast cancer cell migration." (PMID 30819235, 2019). "RBMS3 was reported to have a low expression in breast cancer tissues and cell lines and inhibit the proliferation and metastasis of breast cancer and RBMXL2 was mainly expressed in testis tissue while it had a very low expression in both breast tissue and cancer in Human Protein Atlas database." (PMID 30514345, 2018). "However, RBMS3 has also been documented to exhibit promotive effects in breast cancer." (PMID 38618967, 2024). "The differences in the expression of RBMS3 in cancer cells (both in vivo and in vitro) and the stroma of breast cancer with regard to the molecular status of the tumor may indicate that RBMS3 could be a potential novel target for the development of personalized methods of treatment." (PMID 36769184, 2023). "Hence, we revealed a novel mechanism that RBMS3 could posttranscriptionally regulate Twsit1 expression in breast cancer." (PMID 30819235, 2019). "Moreover, upregulation of RBMS3 was correlated with better prognosis in breast cancer patients." (PMID 30819235, 2019). "The present study gave strong evidences to show that RBMS3 could inhibit breast cancer metastasis." (PMID 30819235, 2019). "At the protein level, the expression levels of RBMS3 in the SK-BR-3 and MDA-MB-231 cell lines were the highest among all the examined breast cancer cell lines and were significantly higher than in MCF-7 and BT-474 cell lines." (PMID 36769184, 2023). "RBMS3 is a novel candidate gene for suppressing tumors as in esophageal squamous cell carcinoma (ESCC), breast cancer, nasopharyngeal cancer (NPC), and lung squamous cell carcinoma (LSCC)." (PMID 36897170, 2023). "Consistent with the tumor-suppressive role of these two miRNAs, TGFBR3 was reported to suppress breast cancer progression through TGF-beta signaling, and RBMS3 and PTPN14 were also shown to play roles in inhibiting metastasis." (PMID 32010179, 2019). "By further analysing above EMT-related RBPs and AS in breast cancer tissues in TCGA, it was found that the expression levels of ADAT2, C2orf15, SRP72, PAICS, RBMS3, APOBEC3G, NOA1, ACO1 and the AS of TNC and COL6A3 were significantly correlated with the prognosis of breast cancer patients." (PMID 38783078, 2024). "Conclusively, eight RBPs such as RBMS3 and AS of TNC and COL6A3 could be used as predictors of breast cancer prognosis." (PMID 38783078, 2024). "The results of our experiments apparently support previous studies’ results that indicate the downregulation of RBMS3 expression in breast cancer cells and its correlation with negative estrogen-receptor status." (PMID 36769184, 2023). "The correlation of RBMS3 expression with TNBC and the expression of progesterone receptor may also lead to the distinction of new molecular subtypes of breast cancer based on the analysis of combined biomarkers." (PMID 36769184, 2023). "RBMS3 negatively regulates the expression of Twsit1 and reduces the level of Matrix metalloproteinase 2 (MMP2) induced by Twist1, thus inhibiting the invasion and metastasis of breast cancer cells." (PMID 34804951, 2021). "In summary, our study revealed a novel mechanism of the RBMS3/Twsit1/MMP2 axis in the regulation of invasion and metastasis of breast cancer, which may become a potential molecular marker for breast cancer treatment." (PMID 30819235, 2019). "Whereas, upregulation of RBMS3 could alleviate Twist1-induced MMP2 expression and abrogate migration, metastasis ability of breast cancer cells, correspondingly." (PMID 30819235, 2019). "We also provided a novel mechanism of the RBMS3/Twsit1/MMP2 axis in the regulation of breast cancer invasion and metastasis, which may become a potential molecular marker for breast cancer treatment." (PMID 30819235, 2019).
breast carcinoma (continued). "We found RBMS2, RBMS3, RBMXL2 were the significantly differently expressed RBMs in breast cancer." (PMID 30514345, 2018). "By establishing the correlation network of differential RBPs and differential AS events, we found that RBM47, PCBP3, FRG1, SRP72, RBMS3 and other RBPs may regulate the AS of ITGA6, ADGRE5, TNC, COL6A3 and other cell adhesion genes, which may affect the EMT process of breast cancer cells." (PMID 38783078, 2024). "The results provided in this study support the claim that RBMS3 expression in the TNBC and HER-2-enriched types is similarly high as in the control cell lines, meaning that RBMS3 could possibly act as a suppressor in Lum-A and Lum-B types of breast cancer." (PMID 36769184, 2023).